RPN1 (ribophorin I)
Diseases named in the same sentence as RPN1 in open-access papers (continued):
Sharing a sentence is not in itself a finding about the gene and the disease.
acute coronary syndrome (1 paper, 2024). Signs and symptoms related to acute ischemia of the myocardium secondary to coronary artery disease. "Compared with the acute coronary syndrome (ACS), CD2AP and DSTN were higher expressed in monocytes cell of stable angina pectoris (SAP), and RPN1 was higher expressed in B cell of SAP." (PMID 39666769, 2024).
chronic lymphocytic leukemia (1 paper, 2025). "For instance, HSD17B8 has colocalization with lymphoid leukemia and chronic lymphocytic leukemia; RPN1 has colocalization with myeloproliferative diseases (excluding CML) and polycythaemia vera; and PARP1 has colocalization with myeloproliferative diseases (excluding CML) and polycythaemia vera." (PMID 41048997, 2025).
chronic myeloid leukemia (1 paper, 2025). "For example, myeloproliferative diseases (excluding chronic myeloid leukemia, CML) have the most colocalized genes, including RPN1, BRAP, PPP1CC, ERP29, and PARP1." (PMID 41048997, 2025).
ductal breast carcinoma (1 paper, 2021). "And the mRNA expression of RPN1 in ductal breast carcinoma was 1.684-fold higher than normal tissues in Sorlie’s dataset." (PMID 34778038, 2021).
glioblastoma (1 paper, 2025). The most malignant astrocytic tumor (WHO grade IV). "In our study, the protein expression level of RPN1 was significantly increased in glioblastoma cell lines U87, U251, U118 and U138." (PMID 39993959, 2025).
hypopharyngeal carcinoma (1 paper, 2024). Carcinoma, predominantly squamous cell, arising from the epithelial cells of the hypopharynx. "The patient presented with a rpT3 rpN1 hypopharyngeal carcinoma 12 months later." (PMID 38706595, 2024).
Infertility (1 paper, 2025). "Here, we found that knockout of the N-glycosylation-associated protein, RPN1, results in abnormal spermatocyte meiosis and complete infertility in male mice." (PMID 40083683, 2025).
insulinoma (1 paper, 2023). "Interestingly, integral membrane ER resident RBPs (e.g., LRRC59, RPN1, TRAPα) consistently displayed higher RNA-bound protein abundance in rat insulinoma (pancreatic β) cells (832/13) without a comparable change in total abundance." (PMID 37735163, 2023).
kidney cancer (1 paper, 2022). Primary or metastatic malignant neoplasm involving the kidney. "As a crucial part of the UPS system, RPN1 was upregulated in lung and kidney cancer." (PMID 36072976, 2022).
liver cancer (1 paper, 2024). An epithelial or non-epithelial malignant neoplasm that arises from the liver. "Additionally, this study revealed the molecular functions of RPN1 in liver cancer, suggesting its potential as a therapeutic target for this disease." (PMID 38927080, 2024). "Additionally, functional experiments, including CCK8, EdU, clone, and transwell assays, indicated that RPN1 knockdown promoted the proliferative and invasive capacities of liver cancer cells." (PMID 38927080, 2024).
male infertility (1 paper, 2025). The inability of the male to effect fertilization of an ovum after a specified period of unprotected intercourse. "Collectively, these results indicated that deficiency of RPN1 in male germ cells caused abnormal spermatogenesis with substantial levels of apoptosis, ultimately leading to male infertility." (PMID 40083683, 2025).
melanoma (1 paper, 2024). A malignant, usually aggressive tumor composed of atypical, neoplastic melanocytes. "Of these, we focused our analysis on three targets known to be associated with melanoma, CPEB4, RPN1, and HNRNPUL1." (PMID 39771522, 2024). "Simultaneously, three of these proteins intersected with established melanoma-related targets, namely RPN1, CPEB4, and HNRNPUL1." (PMID 39771522, 2024).
peripheral nerve injury (1 paper, 2022). Injury to a peripheral nerve. "Consistent with the expression changes of MOGS, the expressions of many metabolism-associated genes, including DDOST, TUSC3, STT3A, STT3B, RPN1, MAGT1, and GANC, were elevated after peripheral nerve injury." (PMID 35575968, 2022).
rectal tumors (1 paper, 2020). "However, in rectal tumors, we found GAPDH, PUM1, and RPN1 with the most stably expressed reference genes." (PMID 33457124, 2020). "Five promising reference genes GAPDH, Pumilio RNA binding family member 1 (PUM1), beta-2-microglobulin (B2M), ribophorin I (RPN1), and phosphomannomutase 1 (PMM1) were selected from different publications to assess their expression stability in rectal tumors as part of the screening phase." (PMID 33457124, 2020). "GAPDH, RPN1, and PUM1 could be used as a suitable reference gene for gene expression-based qPCR experiments in rectal tumors." (PMID 33457124, 2020).
sarcoma (1 paper, 2024). A usually aggressive malignant neoplasm of the soft tissue or bone. "This study identified three valuable genes (SLC7A11, RPN1, GYS1) associated with disulfidptosis in sarcoma (SARC) and developed a prognostic model." (PMID 38531930, 2024). "Compared to their corresponding normal cell lines, SLC7A11, RPN1, and GYS1 exhibited significantly upregulated mRNA expression in sarcoma cell lines (143B, SW982, and SW872)." (PMID 38531930, 2024).
Testicular atrophy (1 paper, 2025). Wasting (atrophy) of the testicle (the male gonad) manifested by a decrease in size and potentially by a loss of fertility. "We further demonstrated that the meiotic obstruction ultimately resulted in the apoptosis of the Rpn1-SKO spermatocytes, which explained the testicular atrophy observed in the mutant mice." (PMID 40083683, 2025).
Varicose veins (1 paper, 2023). Enlarged and tortuous veins. "However, none of the other identified pleiotropy could completely explain the association with varicose veins, including RPN1, RSPO3, and VAT1." (PMID 37404740, 2023). "We identified eight plasma proteins that are significantly associated with the risk of varicose veins after Bonferroni correction (P < 2.495 × 10−5), with five being protective (LUM, POSTN, RPN1, RSPO3, and VAT1) and three harmful (COLEC11, IRF3, and SARS2)." (PMID 37404740, 2023). "As a result, eight proteins were found to be causally associated with varicose veins, including COLEC11, IRF3, LUM, POSTN, RPN1, RSPO3, SARS2, and VAT1." (PMID 37404740, 2023).
tumor (26 papers, 2016 to 2025). "In senescent tumor cells, the upregulation of ribophorin 1 (RPN1; encoded by RPN1) enhances the N-linked glycosylation of PD-L1, thereby preserving it from degradation and increasing its surface expression, irrespective of continuous transcriptional activity." (PMID 41550427, 2025). "We employed a pan-cancer analysis to explore RPN1 expression and its association with clinical outcomes across multiple tumor types." (PMID 39749324, 2024). "Our analysis shows that RPN1 is involved in immune evasion, correlating with the presence of myeloid dendritic cells, macrophages, and tumor-associated fibroblasts, and influencing T-cell activity." (PMID 39749324, 2024). "Correlation analysis showed that RPN1 expression was significantly positively correlated with the infiltration of tumor-associated fibroblasts and myeloid-derived suppressor cells in multiple cancers." (PMID 39749324, 2024). "We found that RPN1 is universally overexpressed and associated with poor prognosis, playing a crucial role in tumor immune evasion." (PMID 39749324, 2024). "Our analysis identified a correlation between RPN1 expression and infiltration of myeloid dendritic cells, macrophages, and tumor-associated fibroblasts." (PMID 39749324, 2024). "Confirming in vitro results, the VTP–BTZ drug combination was able to improve both p62 and RPN1 accumulation, in association with highest tumor growth inhibition and apoptosis processing." (PMID 35205670, 2022). "RPN1, a key regulator associated with disulfidoptosis, may influence various aspects of tumor biology, including immune evasion and cellular senescence." (PMID 39749324, 2024). "RPN1 (ribonucleoprotein I), a key regulator of membrane-bound glycosylation, is abnormally highly expressed in TNBC.RPN1 enhances the stability of PD-L1 by promoting its glycosylation modification, which mediates tumor cell immune escape." (PMID 40313963, 2025). "RPN1 knockdown led to reduced tumor cell proliferation and induced cellular senescence, marked by increased senescence-associated biomarkers and β-galactosidase activity." (PMID 39749324, 2024). "RPN1 is overexpressed in a wide range of tumor types and correlates with poor clinical outcomes, including overall survival, disease-specific survival, and progression-free intervals." (PMID 39749324, 2024). "By leveraging large-scale cancer datasets, we will elucidate the differential expression patterns and prognostic value of RPN1, thereby enhancing our understanding of its involvement in tumor biology." (PMID 39749324, 2024). "Analysis of pan-cancer DNA copy number data from the TCGA database revealed an increase in RPN1 copy number in the majority of tumor types." (PMID 39749324, 2024). "We demonstrated the effects of RPN1 knockdown on subcutaneous tumor formation using shNC and shRPN1 stably transfected H1299 cancer cells in nude mice." (PMID 39749324, 2024). "Based on the pan-cancer dataset combining TCGA and GTEx databases, RPN1 was found to be significantly upregulated in the majority of tumor types (P < 0.05)." (PMID 39749324, 2024). "Our findings reveal distinct chromosomal mappings and expression profiles of DRGs, notably the downregulation of NDUFA11 and upregulation of RPN1 in tumor tissues." (PMID 38549669, 2024). "Variants in 5 genes (RPN1, CDKN2A, HRAS, PALB2, CBFA2T3) have been identified in 32 individuals with tumor from the extended cohort and classified as pathogenic, likely pathogenic, and VUS." (PMID 36845707, 2023). "These phenomena indicated that the RPN1 played a pro-tumor role by maintaining the endoplasmic reticulum homoeostasis in BLBC cells." (PMID 34778038, 2021). "Notably, expression profiling reveals a distinct downregulation of NDUFA11 in tumor tissues, in contrast to the upregulation observed for RPN1; the expression of the other genes remained statistically unaltered between normal and tumor samples." (PMID 38549669, 2024).
tumor (continued). "In vitro and in vivo experiments demonstrated that RPN1 could inhibit tumor progression and promote tumor cell senescence." (PMID 39749324, 2024). "Targeting RPN1 could enhance immunotherapy efficacy and help mitigate tumor progression, offering a potential strategy for cancer treatment." (PMID 39749324, 2024). "Moreover, paired t-test analysis revealed that RPN1 is significantly upregulated in paired tumor samples across several cancer types (P < 0.05)." (PMID 39749324, 2024). "RPN1 is involved in N-glycosylation and was found (among other genes) to be downregulated upon treatment of androgen-independent PCa xenografts with 17β oestradiol that led to inhibition of tumour growth." (PMID 32878211, 2020). "Additionally, cellular senescence markers were assessed in RPN1 knockdown tumor cells." (PMID 39749324, 2024). "Furthermore, aberrant expression of RPN1, a component of the 26S proteasome motif involved in the cell cycle and protein degradation, may affect tumor proliferation." (PMID 38431573, 2024). "The expression of SLC7A11, SLC3A2, RPN1 and NCKAP1 were found to be upregulated in the tumor tissues compared with that in the corresponding normal tissues from the TCGA data." (PMID 38528532, 2024). "Zheng and colleagues' research revealed that the level of RPN1 expression was increased in both HCC cells and tumor samples obtained from patients with HCC." (PMID 39308675, 2024). "In a word, these results implied that higher expression of most OST members, especially RPN1 and RPN2, were significantly correlated with poor prognostic outcome and might play a pro-tumor function." (PMID 34778038, 2021). "Normal liver tissue had negative or medium NCKAP1, RAC1, RPN1, and WASF2 IHC staining, while tumor tissues had medium or strong staining." (PMID 38968580, 2024).
cancer (21 papers, 2016 to 2025). A tumor composed of atypical neoplastic, often pleomorphic cells that invade other tissues. "Our comprehensive analysis across various cancer types revealed widespread upregulation of RPN1 and its association with poor patient survival outcomes, suggesting a critical role for this protein in driving malignant transformation and disease progression." (PMID 39749324, 2024). "RPN1 expression has been linked to elevated expression in 30 cancer types, particularly GBM and PAAD." (PMID 38968580, 2024). "Though it is a critical subunit of OST, the association between RPN1 and cancers has rarely been reported." (PMID 34778038, 2021). "In this study, we confirmed the upregulation of RPN1 in nearly all cancers based on transcriptomic data from the TCGA and GEO databases and proteomic data from the CPTAC database." (PMID 39749324, 2024). "Although prior studies have highlighted the role of RPN2 in various cancers, the impact of RPN1 has been relatively understudied." (PMID 39749324, 2024). "In the current study, we thoroughly examined the mRNA levels of NCKAP1, SLC7A11, WASF2, RAC1, SLC3A2, and RPN1 as well as the relationships between the mRNA levels of these six genes in pan-cancer." (PMID 38968580, 2024). "This study aims to dissect the role of RPN1 in pan-cancer and its potential as a therapeutic target." (PMID 39749324, 2024). "In this study, we systematically investigated the pan-cancer significance of RPN1, elucidating its functional relevance, transcriptional and epigenetic regulation, and potential as a therapeutic target." (PMID 39749324, 2024). "qPCR analysis confirmed a significant increase in the average RPN1 copy number in several cancer cell lines." (PMID 39749324, 2024). "To further evaluate the significance of RPN1 in cancer progression, we analyzed the correlation between RPN1 expression and oncogene expression across pan-cancer samples." (PMID 39749324, 2024). "For macrophages, a high correlation with RPN1 expression was noted in 13 cancer types (r > 0.2, P < 0.05)." (PMID 39749324, 2024). "In summary, this study comprehensively reveals the important biological functions of RPN1 as a key pan-cancer regulator, providing a vital basis for developing potential therapeutic strategies targeting RPN1." (PMID 39749324, 2024). "This study aims to address this gap by systematically analyzing the expression and biological and clinical significance of RPN1 across various cancer types using bioinformatics approaches." (PMID 39749324, 2024). "Despite the potential significance of RPN1, its comprehensive role across various cancers remains underexplored." (PMID 39749324, 2024). "From the CPTAC database, we observed that RPN1 protein expression is significantly higher in various cancers compared to normal tissues (P < 0.05)." (PMID 39749324, 2024). "Specifically, for myeloid dendritic cells, high correlation with RPN1 expression was observed in 10 cancer types (r > 0.2, P < 0.05)." (PMID 39749324, 2024). "For SIGLEC7, 12 cancer types exhibited significant correlation with RPN1 expression (r > 0.2, P < 0.05)." (PMID 39749324, 2024). "Changes in RPN1 levels can affect cell proliferation, migration, and angiogenesis, which are crucial processes in cancer progression." (PMID 38302629, 2024). "Variants in three genes (RPN1, HRAS and PALB2) were carried by several individuals with cancer in extended cohort." (PMID 36845707, 2023). "RPN1 is involved in the N-glycosylation of proteins, whose dysregulation in cancers began to be deciphered at the molecular level during the last decade, with interesting prospects for innovative therapies." (PMID 33207594, 2020). "Of the 102 driver genes present in at least four networks, we found that PSMA, PSMB, and PSMD were the cancer driver genes with a crucial role in the proteasome pathway (with also RPN1/2, PSMA3/5/6/7, PSMB2/3/4/8/9, PSMD2/3/4/7/11/12/14)." (PMID 29304754, 2018).
cancer (continued). "Importantly, further COX analysis indicated that RPN1 is correlated with OS, DSS, DFI, and PFI in various cancers, serving as a risk factor (HR > 1, P < 0.05)." (PMID 39749324, 2024). "This study systematically elucidates the significant role of RPN1 in a pan-cancer context." (PMID 39749324, 2024). "Additionally, high-throughput transcriptomic data for various cancer types obtained from the GEO database indicated that RPN1 is significantly upregulated in multiple tumors (P < 0.05)." (PMID 39749324, 2024). "Additionally, the correlation analysis of immune checkpoint genes (ICGs) expression indicated that RPN1 is correlated with several ICGs across various cancers." (PMID 39749324, 2024). "Similarly, for SIRPA, a significant correlation with RPN1 expression was found in 12 cancer types (r > 0.2, P < 0.05)." (PMID 39749324, 2024). "Furthermore, transcriptomic data from the CPTAC cancer dataset also showed significant upregulation of RPN1 in several tumors (P < 0.05)." (PMID 39749324, 2024). "Moreover, RPN1 was significantly negatively correlated with T cell dysfunction and significantly positively correlated with T cell exclusion across various cancers." (PMID 39749324, 2024). "Emerging studies suggest that RPN1 may play a role in cancer progression." (PMID 38302629, 2024). "Additionally, we will validate these findings through in vitro and in vivo experiments to elucidate the functional relevance of RPN1 and its potential as a therapeutic target, providing valuable insights into the complex mechanisms of cancer cell death and survival." (PMID 39749324, 2024). "However, scant research has been done on the effect of RPN1 on cancers." (PMID 38302629, 2024). "Correlation analysis using transcriptomic data from the TCGA database revealed that RPN1 expression positively correlates with the ER stress-related genes PERK (EIF2AK3) and ATF6 in multiple cancer types." (PMID 39749324, 2024). "The results revealed that SLC7A11, SLC3A2, RPN1, LRPPRC, and GYS1 were highly expressed in several cancer tissues." (PMID 38271056, 2024). "To investigate the role of four disulfidptosis-related genes (SLC7A11, SLC3A2, RPN1, and NCKAP1) in cancer progression, we divided TCGA patients into high and low expression groups based on the median expression levels of these four genes." (PMID 38166898, 2024). "However, the potential mechanism of RPN1 on cancer cell progression is still unknown." (PMID 38302629, 2024). "We found that the expression of GYS1 and SLC7A11 were upregulated, while those of NCKAP1, NDUFS1, NUBPL, OXSM, RPN1, and SLC3A2 were downregulated in ccRCC tissues compared with those in the para-carcinoma tissues." (PMID 38271056, 2024). "The cross-tissue analysis of 12 cancer types revealed that the most stably expressed genes were: PUM1 (SExp = 70), IPO8 (SExp = 61), UBC (SExp = 60), ACTB (SExp = 55), and RPN1 (SExp = 54)." (PMID 30881377, 2019). "Previous study indicated that RPN2 expression predicted response to docetaxel in oesophageal squamous cell carcinoma, while few studies reported the biological role of Ribophorin I (RPN1) in the occurrence and progression of cancers." (PMID 30940778, 2019). "Moreover, in three cancer cell lines (A549, MGC-803, and SW480), we analyzed the expression changes of PERK and ATF6 following RPN1 knockdown." (PMID 39749324, 2024). "Notably, NDUFA11, OXSM, LRPPRC, NCKAP1, RPN1, SLC3A2, and SLC7A11 were upregulated in cancer tissues, while NDUFS1 showed the opposite trend." (PMID 38213838, 2023). "The RPN1 gene (0 pseudogenes, 1 transcript isoform), which was previously suggested by us for normalization of qPCR data in LUAD, LUSC, KIRC, KIRP, and COAD, demonstrate stable expression in these cancer types as well as in PRAD, LIHC, and THCA." (PMID 30881377, 2019). "Notably, RPN1, NUBPL, and OXSM demonstrate widespread CNV across various cancers." (PMID 38397869, 2024).
cancer (continued). "However, some studies have revealed that RPN2 plays a critical role in different cancers, while there was almost no study reporting the effect of RPN1." (PMID 34778038, 2021).